DEFB136 (defensin beta 136)
Description:
Host defense peptide that exhibits antibacterial and antifungal activity. Exhibits antimicrobial activity against E.coli, S.aureus and C.albicans (in vitro). Has high lipopolysaccharide (LPS)-binding affinity, and may thereby be involved in immunoregulation through LPS neutralization.
Synonyms: DEFB137
Tractability: Antibody: UniProt places it where antibodies can reach, with medium confidence; UniProt predicts a signal peptide or a membrane-spanning region; its Gene Ontology location is reachable by antibodies, with medium confidence.
Gene: Protein-coding gene on chromosome 8 (11,973,937 to 11,974,599, reverse strand). Ensembl gene ENSG00000205884.
Subcellular location: Secreted
Pathways (Reactome):
Immune System: Beta defensins; Defensins
Gene Ontology:
Molecular function: lipopolysaccharide binding
Biological process: antibacterial innate immune response; antifungal innate immune response; defense response to Gram-negative bacterium; defense response to Gram-positive bacterium; defense response to bacterium
Cellular component: extracellular region
Genetic constraint (gnomAD): Loss-of-function variants: 7 observed, 3 expected, observed/expected ratio (o/e) 2.33. That is too few expected variants to judge how well the gene tolerates losing a copy. Missense variants: 126 observed, 101.43 expected, observed/expected ratio (o/e) 1.24, 90% interval 1.07 to 1.44. Synonymous variants: 47 observed, 35.93 expected, observed/expected ratio (o/e) 1.31, 90% interval 1.03 to 1.67.
Homologues: Orthologues: chimpanzee DEFB136 (97% identical), macaque DEFB136 (91% identical), dog DEFB136 (65% identical), rabbit DEFB136 (64% identical), guinea pig DEFB136 (55% identical), mouse Defb42 (50% identical), pig DEFB136 (50% identical), rat Defb44 (47% identical).